BRCA1 (BRCA1 DNA repair associated)
Diseases named in the same sentence as BRCA1 in open-access papers (continued):
Sharing a sentence is not in itself a finding about the gene and the disease.
Lynch syndrome (continued). "The majority of tests were for BRCA1/2 (70%), with 10% for mismatch repair genes (Lynch Syndrome) and 22% reporting other genetic tests." (PMID 27980798, 2016). "BRCA1 and BRCA2 together accounted for 50.5% of all positive findings, Lynch syndrome genes for 14.3%, and moderate or less well-defined risk genes for 33.0%." (PMID 26681312, 2016). "Collectively, men with germline mutations in BRCA1, BRCA2 or HNPCC (Lynch syndrome) are reported to be at increased risk of developing PC." (PMID 27456091, 2016). "Michigan used cancer registry data from 2006 through 2007 to identify more than 15,000 people needing evaluation for BRCA1 or BRCA2 or Lynch syndrome by the end of 2012." (PMID 24921900, 2014). "In Lynch syndrome slightly more cascade tests were performed in the first two years potentially reflecting the increased actionability in males with 42.2% of pre-symptomatic tests in males compared to 25.8% in BRCA1/2 (p < 0.0001)." (PMID 38478259, 2024). "Risk-reducing gynecological surgery (RRGS) is a prophylactic procedure that may be offered to BRCA1, BRCA2, and Lynch syndrome (LS) mutation carriers to reduce the risk of developing gynecological cancer." (PMID 38698439, 2024). "A potential young below 50 years subjects with high risk to hereditary cancer including Lynch Syndrome and BRCA1/2 predisposition cancer are not accepted in screening and don’t impact on possible changes in improving of early diagnosis theses cancers." (PMID 39529133, 2024). "The most significant risk factor for OC development are germline pathogenic/likely pathogenic variants (GPVs) in OC predisposition genes (including BRCA1, BRCA2, BRIP1, RAD51C, RAD51D, Lynch syndrome genes, or BRIP1), which contribute to the development of over 20% of all OC cases." (PMID 38069345, 2023). "Furthermore, a combined 27% of participants who had genetic testing reported a mutation in BRCA1 (12%), BRCA2 (7%) or in another OC gene (8%; most commonly RAD51C/D, CHEK2 and the Lynch Syndrome genes)." (PMID 35621661, 2022). "The PV carriers in Lynch syndrome genes and BRCA1/BRCA2 could benefit from treatment with immune checkpoint (PD-1/PD-L1 inhibitors) and PARP (PARPi) inhibitors, respectively." (PMID 36612198, 2022). "Similarly, BRCA1, BRCA2 and PMS2 were also reported as germline mutations in cancers other than Lynch syndrome and HBOC." (PMID 36451132, 2022). "The CPGs with the highest numbers of non-index positive cases identified on cascade testing were BRCA1/2 (n = 1999) and the mismatch repair CPGs associated with Lynch Syndrome (n = 731)." (PMID 34866136, 2021). "Unlike other hereditary cancer syndrome such as Lynch syndrome, no definite hot spot BRCA1/2 mutations were found in several populations." (PMID 33563323, 2021). "Likewise, more than half (53.8%) of PVs in patients meeting only Lynch criteria were in non–Lynch syndrome genes, including 8.8% in BRCA1/2." (PMID 31406321, 2020).
Lynch syndrome (continued). "While we attempted to minimize potential confounding effects introduced by other cancers, we did not control for family history in these analyses, although family history was incorporated where applicable when assessing BRCA1/2 and Lynch syndrome testing criteria." (PMID 31406321, 2020). "20.2% (93/460) were assessed to also have features suggestive of alternative hereditary cancer syndromes, most commonly Lynch Syndrome (65, 69.9%), Li Fraumeni (11, 11.8%) and Cowden Syndrome (11, 11.8%) which have overlapping phenotypes with BRCA1/2 hereditary breast cancer syndrome." (PMID 30875412, 2019). "BRCA1/2 and Lynch syndrome testing were the most frequently offered genetic tests." (PMID 31275354, 2019). "The two genetic mutations recorded were of BRCA1/2 and MSH6 causing Lynch syndrome." (PMID 30309438, 2018). "These services included testing for the BRCA1 or BRCA2 mutation in patients without cancer who met US Task Force on Preventive Services guidelines as well as genetic testing for Lynch syndrome according to National Comprehensive Cancer Network guidelines." (PMID 24921900, 2014). "Cancer survivors with a family history of cancer may be at high risk of SPC, with most common syndromes identified to date including mutations in BRCA1 and BRCA2 genes and Lynch syndrome." (PMID 24528929, 2014). "There were no instances of MPNST amongst 5727 BRCA1/2 carriers and first degree relatives, nor among 2029 Mismatch Repair mutation carriers and first degree relatives from Lynch syndrome families." (PMID 23036231, 2012). "In addition, woman with a suspected high-risk hereditary cancer syndrome (BRCA1 and BRCA2 mutation and Lynch syndrome) should receive genetic counselling, and, if the mutation is confirmed, to consider prophylactic surgery (risk-reducing bilateral salpingo-oophorectomy)." (PMID 29966369, 2018). "Recommended gene panels prioritize DNA repair and Lynch syndrome genes—with BRCA2, BRCA1, and MMR genes as top targets in metastatic disease." (PMID 41440226, 2025). "These panels usually include DNA damage-repair genes (e.g., BRCA1, BRCA2, ATM, CHEK2, PALB2), mismatch-repair genes (Lynch syndrome), and syndrome-specific genes such as VHL, FH, FLCN, and MET." (PMID 41440226, 2025). "These early guidelines did not set specific thresholds for genetic testing but, emphasised the importance of testing high risk individuals with cancer to open the possibility of testing for BRCA1, BRCA2 and Lynch syndrome genes." (PMID 38478259, 2024). "From 5605 records reviewed, 9 studies (4 randomised control trials and 5 cohort studies) were included involving families with BRCA1, BRCA2 and Lynch syndrome." (PMID 36253533, 2023). "Across unaffected populations, fewer than 5% of BRCA1 or BRCA2 carriers and fewer than 1% of Lynch syndrome carriers are estimated to have been identified through genetic testing." (PMID 30651894, 2019). "This is especially important given the largely debated topic of population screening for BRCA1, BRCA2, and Lynch syndrome." (PMID 31266460, 2019).
Lynch syndrome (continued). "No pathogenic variants were observed in BRCA1, STK11, CDKN2A, APC, PRSS1, or those genes associated with Lynch syndrome." (PMID 39594734, 2024). "BRCA1/2 HBOC and Lynch syndrome were most often reported cancer syndromes." (PMID 36635046, 2023). "Of note, the patient portal does not capture information beyond the scope of BRCA1 and BRCA2—associated HBOC, such as Li‐Fraumeni syndrome, Lynch syndrome or more moderate‐risk HBOC genes." (PMID 36660874, 2023). "For patients without Lynch syndrome, APC was identified as the gene associated with the most mutations (n = 14) and was followed by BRCA1 (n = 8), RAD50 (n = 7), MUTYH (n = 5), ATM (n = 5), and BRCA2 (n = 4)." (PMID 35014770, 2022). "PVs in BRCA1, but not BRCA2, PALB2, ATM, CHEK2, or Lynch syndrome genes, were associated with elevated RS on multivariable analysis (P < .001)." (PMID 33426465, 2021). "Conversely, 5.8 % of patients with PVs in BRCA1/2 and 26.9 % of patients with PVs in Lynch syndrome genes did not meet respective testing criteria." (PMID 34289891, 2021). "In addition, 5.8% of patients with PVs in BRCA1/2 and 26.9% of patients with PVs in Lynch syndrome genes did not meet respective testing criteria." (PMID 31406321, 2020). "There could be some confidence therefore that MPNST does not occur at increased incidence in BRCA1/2 carriers but not yet in Lynch syndrome." (PMID 23036231, 2012). "Consequently, BRCA1/2 and Lynch syndrome testing criteria are not highly specific to these genes." (PMID 31406321, 2020). "Moreover, the results of OC surveillance in women with BRCA1 and BRCA2 mutations may not be directly applicable to Lynch syndrome due to significant biological differences between OC in Lynch syndrome and OC seen in hereditary ovarian and breast cancer syndrome." (PMID 39768893, 2024).
ovarian tumors (178 papers, 1999 to 2026). "To establish the feasibility of this technique, we collected 27 FT lavages from high‐risk BRCA1/2 mutation carriers, ovarian neoplasm (ON) patients, and control individuals with benign or non‐tubal gynaecological conditions (Supplementary Discussions 1 and 2)." (PMID 41482634, 2026). "Hierarchical clustering of the different risk/ovarian neoplasm groups revealed that BRCA1/2‐mutated groups showed similar protein profiles." (PMID 41482634, 2026). "The results of clinical trials exploring synthetic lethality using PARP inhibitors as a treatment for platinum-sensitive BRCA1/2-mutated breast and ovarian tumors are promising." (PMID 40661778, 2025). "By contrast, only high-impact BRCA1 variants occurred much more frequently in hgOvCa than in all the other ovarian tumor groups." (PMID 39456660, 2024). "PTEN loss has been found in 30% of BRCA1 germline or somatic mutated ovarian tumours, similar to what is observed in the IGROV-1 cell line." (PMID 38940864, 2024). "BRCA1 hypermethylation is found in approximately 10% of ovarian tumors and is associated with high levels of genomic instability." (PMID 39695768, 2024). "Regulatory regulators have approved PAPRi as a monotherapy for BRCA1/2 mutant breast and ovarian tumors, and concepts for DNA repair‐targeted therapy in malignancies with mutations in the BRCA1 or BRCA2 tumor suppressor genes are now available." (PMID 37808268, 2023). "In this multicentre study, we evaluated the association of ovarian tumour histology with germline BRCA1 and BRCA2 pathogenic variant status." (PMID 37076566, 2023). "On the other hand, loss of function mutations of BRCA1, which often occur at the early stages of breast and ovarian tumors, have been associated to epithelial-to-mesenchymal transition and transcriptional reprogramming of luminal cells into basal cells." (PMID 37887275, 2023). "Fifteen percent of ovarian tumors carry mutations in BRCA1 or BRCA2, rendering them vulnerable to treatment with PARP inhibitors such as olaparib." (PMID 37568736, 2023). "We assessed HRD, aneuploidy, somatic mutations, copy number variation, and global transcription in paired BRCA1/2 mutation-associated breast and ovarian tumors, focusing on features associated with recurrence." (PMID 36344544, 2022). "In our system, the SASP program triggered by cisplatin therapy in Brca1-deficient ovarian tumors was limited to Ccl5, Cxcl10, and Il6 of the factors examined." (PMID 35082152, 2022). "Further validation of key results (LOH transitions, PARP1 amplifications, BRCA2 isoform switching) in an independent cohort of paired primary and recurrent BRCA1/2 mutation-associated breast and ovarian tumors will be important." (PMID 36344544, 2022). "We have previously shown that activation of the STING pathway in myeloid cells triggered by dsDNA fragments released from BRCA1-deficient ovarian tumor cells upon PARPi is required for the anti-tumor activity of PARPi16." (PMID 35641483, 2022). "In ovarian tumors, a functional HR system and intact BRCA1/2 function are often associated with resistance to platinum-based chemotherapy and PARP inhibitors." (PMID 35736348, 2022). "PARP inhibitors such as olaparib and pamiparib have been demonstrated to be indicative of monotherapy in patients with ovarian tumor harboring BRCA1 or BRCA2 mutations." (PMID 35910366, 2022). "To further validate these results, we assessed BRCA2 isoform expression in an independent cohort of 42 BRCA1/2 mutation-associated primary breast and ovarian tumors." (PMID 36344544, 2022). "As the average log2(counts per million) for individual genes were similar between breast and ovarian tumors overall (R2 = 0.934), we combined all BRCA1/2 mutation-associated tumors to identify the major transcriptomic differences compared to normal tissues." (PMID 36344544, 2022).
ovarian tumors (continued). "Our study follows a multilayered approach with the addition of valuable ubiquitination profiling of ovarian tumors as well as providing new information on proteome, phosphorylation and ubiquitination profiling according to the BRCA1 mutational status." (PMID 35292711, 2022). "Firstly, in HGS-EOC cases the mutational profile of the BRCA1/2 genes in ovarian tumor biopsies barely mirrors that of their own synchronous lesions." (PMID 34853661, 2021). "The only LS case whose ovarian tumour was MMR proficient was a patient with a clear cell carcinoma who also had a constitutional BRCA1 pathogenic variant." (PMID 32917768, 2021). "BRCA1/2-driven ovarian tumors usually develop via inactivation of the remaining allele of the involved gene." (PMID 33536037, 2021). "PARP inhibitors yield interesting outcomes for patients with ovarian tumors harboring BRCA1 or BRCA2 mutation, but also with other tumors with homologous repair (HR) deficiency." (PMID 34206535, 2021). "First, we examined formalin-fixed, paraffin-embedded (FFPE) tissue samples from the ovarian tumor of the patient by BRCA1/2 all-exon sequencing and found a point mutation (G>T) in the c.7795 position in the exon 16 of the BRCA2 gene." (PMID 34068254, 2021). "BRCA1 mutations are closely related to the tumorigenesis and progression of female breast and ovarian tumours." (PMID 33611848, 2021). "For example, BRCA1/2-mutated ovarian tumors showed increased expression levels of PD-1/PD-L1 and tumor-infiltrating lymphocytes (TIL), such as CD3+ and CD8+ TILs." (PMID 33680909, 2020). "To put this data into perspective we examined the classification of all BRCA1/2 germline mutation related breast and ovarian tumors from The Cancer Genome Atlas (TCGA) datasets." (PMID 32164626, 2020). "Although loss of BECN1 is purported to be solely a passenger mutation "piggybacking" on a BRCA1 deletion during tumorigenesis, we directly observed formation of earlier ovarian tumors in Becn1+/- MISIIR-TAg+ mice compared to Becn1+/+ MISIIR-TAg+ mice." (PMID 31923184, 2020). "Jazaeri and colleagues quantified gene expression for 61 ovarian tumours, which included 18 BRCA1- and 16 BRCA2-associated tumours." (PMID 33081408, 2020). "Poly-ADP-ribose-polymerase inhibitor (PARPi) treatment is indicated for advanced-stage ovarian tumors with BRCA1/2 deficiency." (PMID 32483276, 2020). "Subsequently, BRCA1-associated ovarian tumours were shown to be enriched for immunoreactive (C2) subtype, which is characterised by lymphocytic infiltrate in the epithelium." (PMID 33081408, 2020). "As expected, breast and ovarian tumors from BRCA1/2 germline mutation carriers have even higher HR deficiency scores (average value > 50 for BRCA2 and > 60 for BRCA1 mutation carriers)." (PMID 32164626, 2020). "In this study, LOH was observed in 91 and 67% of ovarian tumors with a BRCA1 and BRCA2 germline pathogenic mutation, respectively, which is in accordance with previous reports." (PMID 32850417, 2020). "In this study, we have demonstrated that ~20% of the ovarian tumors can be identified with a pathogenic SNV/indel in BRCA1/2 while another ~10% will have a pathogenic CNV or a promoter DNA methylation defect in these genes." (PMID 32483276, 2020). "Clinical validation of such approaches, commonly described as synthetic lethality (SL), has been provided by the regulatory approval of poly(ADP-ribose) polymerase 1 inhibitors (PARPi) as monotherapy for BRCA1/2-mutated breast and ovarian tumors." (PMID 31921645, 2019). "Recently, BRCA1 and BRCA2 somatic mutations were detected in circulating free DNA of breast and ovarian tumors resistant to platinum-based therapy and to PARPi in patients with BRCA1 and BRCA2 germline mutations." (PMID 30669514, 2019). "Consistent with this possibility, deep ZC3H18 deletions and low ZC3H18 mRNA levels are nearly mutually exclusive with BRCA1 driver mutations and deep deletions in ovarian tumors analyzed by The Cancer Genome Atlas research network." (PMID 31604914, 2019).